FOXM1 (forkhead box M1)
Diseases named in the same sentence as FOXM1 in open-access papers (continued):
Sharing a sentence is not in itself a finding about the gene and the disease.
breast cancer (continued). "Indeed, treatment of USP22-null cells with the proteasome inhibitor MG132 largely restored FoxM1 expression to a level comparable to that in WT breast cancer cells." (PMID 37398311, 2023). "By providing an alternative means of targeting the cell-cycle deregulation and accelerated proliferation typical of aggressive luminal breast cancers, interfering with the c-Src–FOXM1 positive feedback loop may improve patient outcomes." (PMID 36795481, 2023). "Biotin-labeled M1-20 could bind to endogenous Foxm1 from mouse breast cancer 4T1 cell lysates and as expected, M1-20 inhibited 4T1 cells at a dose-dependent manner." (PMID 37598210, 2023). "Thus, FOXM1 overexpression in all breast cancer subtypes make its inhibition a very attractive approach for impeding the progression of all breast cancer subtypes." (PMID 37370117, 2023). "USP22 functions as a de novo FoxM1-specific deubiquitinase in breast cancer cells." (PMID 37398311, 2023). "The c-Src/FOXM1–dependent transcriptional program includes many key regulators of G2/M and mitotic progression as well as c-Src itself, forming a positive feedback loop that drives breast cancer cell proliferation and metastasis." (PMID 36795481, 2023). "Likewise, the impaired ability in colony formation of 4T1 breast cancer cells by USP22 depletion was largely rescued by exogenous FoxM1 expression." (PMID 37398311, 2023). "Thus, FOXM1 KD is detrimental in human breast cancer cells and mouse cells that express high levels of MAD2." (PMID 37452072, 2023). "We discuss new inhibitors of FOXM1 and highlight FOXM1 as an attractive target for controlling drug-resistant and difficult-to-suppress breast cancers, and how blocking FOXM1 might improve outcomes for patients with all subtypes of breast cancer." (PMID 37370117, 2023). "Notably, brain metastases from breast cancer patients were found to be enriched for cell cycle and G2/M pathways driven by FOXM1." (PMID 37370117, 2023). "We identified a positive correlation between FOXM1 and c-Src expression in human breast cancer and show that the expression of FOXM1 target genes predicts poor outcomes and associates with the luminal B subtype, which responds poorly to currently approved therapies." (PMID 36795481, 2023). "Our study showed that FOXM1 mediated DNA damage response could be targeted using miR-4521 mimics as a novel therapeutic for breast cancer." (PMID 37025658, 2023). "FOXM1 controls breast cancer mitosis and EMT, coupled with proliferation." (PMID 37626655, 2023). "Similarly, the Kaplan-Meier survival analysis curve also showed that the high FOXM1 expression correlates with the poor survival in breast cancer patients." (PMID 37025658, 2023). "Overexpression of miR-4521 significantly downregulated FOXM1 expression in breast cancer cells." (PMID 37025658, 2023). "We demonstrate that recently discovered compounds that bind FOXM1 and trigger small-molecule–induced degradation via the proteasome are effective across multiple models of luminal B–like breast cancer, establishing a potential indication for the clinical translation of these compounds." (PMID 36795481, 2023). "However, FOXM1 has been reported to act as a negative regulator of senescence in squamous carcinoma cells, breast cancer, and gastric cancer." (PMID 36622275, 2023). "Positive correlation of USP22, FoxM1 and integrin b1 in human breast cancer." (PMID 37398311, 2023). "FOXM1 expression is also highly correlated with HER2 expression in breast cancer." (PMID 37370117, 2023). "In addition, FOXM1 is known to promote cellular resistance to epirubicin, a genotoxic drug used to treat breast cancer." (PMID 38264570, 2023). "FOXM1 also increases the cancer stem cell population and blocks cell senescence and apoptosis, contributing to the survival, progression, and metastasis of breast cancer." (PMID 37370117, 2023).
breast cancer (continued). "Overexpression of miR-4521 in breast cancer cell led to ROS induced DNA damage and increased cell death suggesting its potential as novel FOXM1 inhibitor which can be further exploited in breast cancer mouse model alone or in combination with platinum drugs or PARP inhibitor." (PMID 37025658, 2023). "Further characterization by IHC staining show that the levels of USP22, FoxM1 and integrin b1 protein expression by USP22i-S02 treatment, which consequently inhibited the breast cancer cell growth because the percentage of Ki-67+ proliferative cells was dramatically decreased." (PMID 37398311, 2023). "FOXM1 promotes the development of endocrine resistance and chemoresistance in breast cancers." (PMID 37370117, 2023). "Therefore, USP22 controls breast cancer stem cell self-renewal through protecting FoxM1 from ubiquitination-mediated proteasomal degradation to enhance ITGB1 transcription." (PMID 37398311, 2023). "FOXM1 regulates cell cycle progression and DNA damage response in breast cancer." (PMID 37025658, 2023). "In addition, we have shown that FOXM1 increases breast cancer cell aggressiveness, characterized by a migratory and invasive phenotype with modulation of EMT markers like SNAIL, TWIST, CXCR4, and also E-cadherin." (PMID 37370117, 2023). "Similarly, FOXM1 expression is correlated with ERα expression in many breast cancer cell lines, and overexpression of FOXM1 increases ERα expression at both protein and mRNA levels, augmenting its pro-proliferative effect." (PMID 37370117, 2023). "We have conclusively shown that miR-4521 perturbs FOXM1 function and promote significant reduction in cancer cell proliferation, cell cycle arrest at G1 phase, decreased cell migration and reduced expression of mesenchymal marker expression in breast cancer." (PMID 37025658, 2023). "Although breast cancer in vitro and in vivo models were mainly used for analyzing the anti-cancer effects of M1-21 in this study, we believe that M1-21 possesses a broad spectrum inhibiting multiple types of cancer because of its targeting to FOXM1." (PMID 37344857, 2023). "Suppression of FoxM1 is a critical strategy to overcome the metastatic breast cancer progression." (PMID 37689738, 2023). "Because FOXM1 is expressed at all breast cancer stages and in all breast cancer subtypes, FOXM1-targeted therapies hold promise for suppressing early breast cancers as well as advanced drug-resistant forms of breast cancers." (PMID 37370117, 2023). "Taken together, these data suggested that YTHDF1 knockdown blocks the proliferation, migration, and invasion of breast cancer cells, but that could be rescued by FOXM1 overexpression simultaneously." (PMID 35197112, 2022). "In addition, we found that FOXM1 protein expression was highly expressed in breast cancer tissues in The Human Protein Atlas database." (PMID 35197112, 2022). "Moreover, we demonstrated that YTHDF1 played a crucial role in promoting cell proliferation and invasion in cancer cells via the YTHDF1/FOXM1 axis, aggravating breast cancer progression and metastasis consequently." (PMID 35197112, 2022). "We further verified the role of the YTHDF1/FOXM1 axis in breast cancer progression." (PMID 35197112, 2022). "Moreover, two independent studies demonstrated that E2F1 transcriptionally regulates the expression of FOXM1 in MCF7 breast cancer cells, opposite the direction of transcriptional regulation shown in our study." (PMID 35835838, 2022). "FOXM1 plays a role in regulating radiosensitivity in glioma and breast cancer cells, and FOXM1 may enhance radiation resistance in part by inducing KIF20A expression." (PMID 35574421, 2022).
breast cancer (continued). "FOXM1 is overexpressed and plays a critical role in tumorigenesis, metastasis, and drug resistance in a broad range of human cancer types, such as lung, gastric, and breast cancers." (PMID 35139887, 2022). "We acquired the ChIP-seq data of FOXM1 targeting NEIL3 in breast cancer from Cistrome Data Browser." (PMID 35392496, 2022). "Our study reveals a novel YTHDF1/FOXM1 regulatory pathway that contributes to metastasis and progression of breast cancer, suggesting that YTHDF1 might be applied as a potential biomarker and therapeutic target." (PMID 35197112, 2022). "In breast cancer, FOXM1 was shown to promote EMT by facilitating Slug gene transcription." (PMID 35197112, 2022). "However, intracellular FoxM1 protein level was minimally affected by FDI-6 treatment on breast cancer cells." (PMID 35884976, 2022). "However, ACSL4 also negatively affects radiosensitivity in breast cancer by regulating forkhead box M1 (FOXM1) to enhance the DNA damage response and inhibit apoptosis." (PMID 36176274, 2022). "Whereas overexpression of FOXM1 in breast cancer cells partially counteracted the tumor suppressed effects caused by YTHDF1 silence, which further verified the regulatory relationship between YTHDF1 and FOXM1." (PMID 35197112, 2022). "However, ALKBH5 has been demonstrated to be an oncogene in glioblastoma through the modification of FOXM1, in breast cancer through m6A demethylation of NANOG, and in acute myeloid leukemia via AXL m6A modification." (PMID 35395767, 2022). "In addition, FOXM1 has been shown to play a key role in PTX resistance in breast cancer and ovarian cancer." (PMID 34768915, 2021). "Besides, it is reported that knocking out FOXM1 in breast cancer cells can restore sensitivity to endocrine therapy and FOXM1 plays a role in the development of HER2-targeted therapy resistance." (PMID 34977029, 2021). "In HER2+/HR+ breast cancer cell lines, the combination of the two drugs could further reduce FOXM1 phosphorylation, thereby enhancing the antitumor effect to a certain extent." (PMID 34977029, 2021). "Furthermore, here, we propose a GRN kinetic signature based on FOXM1-targeted gene interactions to prognosticate relapse in breast cancer." (PMID 33667222, 2021). "Our understanding of how FOXM1 inhibitors suppress breast cancer growth and aggressiveness and how breast cancer cells can defeat their effectiveness and acquire resistance should be helpful in directing further studies to move these agents towards translation into the clinic." (PMID 34944900, 2021). "Overexpression of FOXM1 and ERBB2 lead to genomic instability and uncontrolled cell division and malignancy, which are associated with poor prognosis in various cancerous lesions including breast cancers." (PMID 34565361, 2021). "Oncogenic transcription factor FOXM1 is overexpressed in breast cancer and plays important roles in DNA damage repair by regulating the expression of genes essential for DNA damage sensing, mediation, signaling, and repair, as well as for cell cycle and cell death control." (PMID 34880209, 2021). "Moreover, we tested the statistical significance of the FOXM1-targets interactions in predicting relapse in breast cancer using a bootstrapping approach." (PMID 33667222, 2021). "The loss of RASSF1A or aberrations in the function of the Hippo-kinases LATS1 and 2 might shift the balance towards increased activation of YAP1, FOXM1 and ERα, fostering luminal breast cancer initiation and progression." (PMID 34831091, 2021). "In addition, inhibiting FOXM1 has been shown to induce apoptosis in several cancer cell types, including breast cancer, ovarian cancer, and nasopharyngeal carcinoma." (PMID 34206484, 2021). "We need to further investigate the effect of FOXM1 on HER2+/HR+ breast cancer at the tissue level." (PMID 34977029, 2021). "Thus, their results hint that miR-671-5p radiosensitizes breast cancer cells by targeting the FOXM1 target, affecting downstream genes involved in DNA repair." (PMID 34804940, 2021).
breast cancer (continued). "In summary, we speculated that SHR6390-combined pyrotinib inhibited the proliferation of HER2+/HR+ breast cancer through FOXM1." (PMID 34977029, 2021). "Increased expression of FOXM1 is identified in multiple human cancers, including ovarian cancer, breast cancer, prostate cancer, hepatocellular carcinoma, colorectal cancer, melanoma, lung cancer, and gastric cancer, which indicates a poor prognosis in most solid tumors." (PMID 33937262, 2021). "We verified significant associations between FOXM1 and the distant metastasis-free survival (DMFS), relapse-free survival (RFS) and overall survival (OS) and therapeutic responses in breast cancer patients, in consistent with previous clinical studies." (PMID 33667222, 2021). "The importance of FoxM1-MuvB to lung and breast cancer pathogenesis has been described, but further studies in HGSOC are needed to define the molecular mechanisms by which these transcription factors exert their unfavorable effects and assess the routes of potential therapeutic development." (PMID 33747961, 2021). "Moreover, both in vitro and in vivo experiments have validated that FOXM1 plays important roles in breast cancer progression through promoting cell proliferation and cell cycle." (PMID 33667222, 2021). "These and our study identify FOXM1 to be an attractive tumor-specific gene critical for breast cancer development and could be served as a potential therapeutic target for HER2+/HR+ breast cancer." (PMID 34977029, 2021). "For instance, FOXM1 drives breast cancer cell proliferation under transcriptional control by ERα." (PMID 34831189, 2021). "OTUB1 was reported to inhibit the ubiquitination of FOXM1 in ovarian cancer and breast cancer." (PMID 32257108, 2020). "Moreover, we demonstrated that SOX2 feedback inhibits FOXO3a expression by directly transactivating DNMT1, and inhibition of DNMT activity suppressed tumor growth via regulation of FOXO3a/FOXM1/SOX2 signaling in breast cancer." (PMID 31296961, 2020). "FOXM1 is especially upregulated in TNBC compared to the other breast cancer subtypes." (PMID 32961773, 2020). "FOXM1 expression is activated by ERα in the presence of estrogens through direct binding of ERα to an estrogen-response element site within the FOXM1 promoter, consistent with the observation that elevated expression of FOXM1 in breast cancer strongly correlates with ERα expression." (PMID 32967092, 2020). "Additionally, the role of deubiquitinase enzymes like USP5, UCHL3 and USP21 have been demonstrated to stabilize FOXM1 in pancreatic cancer, and basal like breast cancer (BLBC) respectively." (PMID 33680951, 2020). "FOXM1 contributes to chemoresistance in breast cancer by enhancing DNA damage repair." (PMID 33311446, 2020). "Indeed it has been reported that FOXM1 is a key mediator of mitogenic functions of ERα and oestrogen in breast cancer cells, contributing towards tamoxifen resistance." (PMID 32066877, 2020). "In breast cancer, miR-671-5p is a tumor-suppressor miRNA in breast tumorigenesis and works by repressing Forkhead Box M1 (FOXM1), which is an oncogenic transcription factor, and causes epithelial-to-mesenchymal transition (EMT) in MDA-MB-231 breast cancer cells." (PMID 32582694, 2020). "Moreover, FOXM1 expression in breast cancer cells has been shown to be controlled by a nuclear receptor, ERα which directly bind to the ERE like element on FOXM1 promoter." (PMID 33680951, 2020). "Moreover, abnormal activation of FOXM1 also contributes to drug-resistance in cancers including ovarian cancer, breast cancer, prostate cancer, nasopharyngeal carcinoma, acute myeloid leukemia and colorectal cancer." (PMID 33291076, 2020).
breast cancer (continued). "Hence, these new compounds offer intriguing translational opportunities for the development of new anticancer agents, either as mono or combination therapies targeting FOXM1 actions that drive aggressive forms of breast cancer, as well as other cancers." (PMID 31815181, 2019). "Our findings identify and characterize a new class of compounds that effectively antagonize FOXM1 actions and tumor growth, and may be suitable for further clinical evaluation in targeting aggressive breast cancers driven by FOXM1." (PMID 31815181, 2019). "However, in TCGA pan-cancer data, breast cancer (BRCA) showed a lower frequency of FOXM1 mRNA, protein expression, and genomic amplifications compared to HGSC." (PMID 30795624, 2019). "These compounds may be suitable for further clinical evaluation in targeting aggressive breast cancers driven by FOXM1." (PMID 31815181, 2019). "In addition, FOXM1 contributes to drug resistance in breast cancer cells by enhancing DNA-damage repair pathways." (PMID 31391072, 2019). "Furthermore, we demonstrate that HMGA1 and FOXM1 synergistically drive breast cancer cells to promote tumor angiogenesis both in vitro in endothelial cells and in vivo in a zebrafish xenograft model." (PMID 31311575, 2019). "Studies on breast cancer showed that FOXM1 could enhance the resistance of breast cancer to chemotherapy and endocrine therapy by affecting the mitosis of tumor cells, DNA damage repair, and tumor stemness." (PMID 30782607, 2019). "Intriguingly, FOXM1-associated pathway has been found to be the top up-regulated pathway in TNBC but not in other breast cancer subtypes, suggesting a crucial role of FOXM1 in TNBC." (PMID 31311575, 2019). "We propose a model in which PMLIV represses breast cancer proliferation, but it may also promote long‐term survival and/or stress resistance by regulating FOXM1 and FOXO3 transcriptional programs." (PMID 30927552, 2019). "In breast cancer and fatty liver-associated liver cancer, O-GlcNAcylation was previously thought to be a central component linking metabolism to invasion and metastasis via the SIRT1/FOXM1 axis." (PMID 30093632, 2019). "As hypothesized, BBC and HGSC showed similarly increased frequency of FOXM1 amplifications compared to other molecular subtypes of breast cancer." (PMID 30795624, 2019). "Overall, clinical datasets analysis confirmed that VEGFA expression positively correlates with HMGA1 and FOXM1, and that their presence has an impact on breast cancer development, since a signature combining HMGA1, FOXM1 and VEGFA expression is associated to a worse prognosis." (PMID 31311575, 2019). "The exact molecular mechanisms through which ALDH1A1 selectively regulates growth in breast cancer cells is unclear, but could involve FOXM1 and Notch signaling." (PMID 31208996, 2019). "Therefore, the possibility to target HMGA1/FOXM1 in combination should represent an attractive therapeutic option to counteract breast cancer angiogenesis." (PMID 31311575, 2019). "Notably, given that MDA-MB-231 cells were more sensitive to Moracin D than in MCF-7 cells via Wnt3a/FOXM1/β-catenin signaling and activation of caspases, different signaling pathways are expected by Moracin D in two breast cancer cells." (PMID 30201862, 2018). "Furthermore, overexpression of FOXM1 can confer resistance towards tamoxinfen and fulvestrant in endocrine sensitive ER+ve breast cancer cells." (PMID 29180117, 2018). "ONCOMINE analysis revealed that FoxM1 mRNA expression was significantly higher in a wide variety of datasets in different cancer types than corresponding normal samples, especially in sarcoma, lung cancer and breast cancer." (PMID 29416660, 2018). "The mammalian transcription factor FoxM1 is dominantly overexpressed and plays critical role in tumorigenesis, proliferation, and metastasis, as well as drug resistance in a broad range of human cancer types, such as lung, gastric, and breast cancers." (PMID 29416660, 2018).